FRK (fyn related Src family tyrosine kinase)
Diseases named in the same sentence as FRK in open-access papers (continued):
Sharing a sentence is not in itself a finding about the gene and the disease.
breast carcinoma (continued). "Bisulphite sequencing of the promoter region revealed that two of these sites were consistently methylated in FRK-low/negative cell lines and especially in the basal B breast cancer subtype." (PMID 28077797, 2017). "Methylation was largely absent in cell lines with high FRK, with exception of the breast cancer cell lines ZR-75-1 and CAMA-1." (PMID 28077797, 2017). "We found that the FRK promoter is methylated at specific CpG sites in FRK-low/negative breast cancer cell lines and demonstrated that histone deacetylase inhibitors reactivated the expression of FRK in these cells." (PMID 28077797, 2017). "We, however, obtained no significant increase in cell prolif eration when FRK-KM (kinase-defective) mutant was transiently transfected into T47D breast cancer cell line." (PMID 29348886, 2017). "The human fyn-related kinase (FRK) is a non-receptor tyrosine kinase known to have tumor suppressor activity in breast cancer cells." (PMID 29348886, 2017). "Fyn-related kinase (FRK) is a non-receptor tyrosine kinase, reported to be downregulated in breast cancer and gliomas, where it is suggested to have tumor suppressor activity." (PMID 28077797, 2017). "However, the levels of Survivin and MMP-1 were upregulated in FRK knockdown SKBR3 and MCF-7 breast cancer cells." (PMID 29348886, 2017). "It is worth mentioning we observed no change in the level of pSTAT3 with the knockdown of FRK in SKBR3 as well as MCF7 breast cancer cell lines." (PMID 29348886, 2017). "The expression of FRK was detected in breast cancer cell lines such as BT20, MDA-MB-468, and MCF7, but not in BT549, MDA-MB-231, MDA-MB-435 cell lines." (PMID 29348886, 2017). "Observations from both breast cancer cells and TCGA data led to the conclusion that the transcription repression of FRK was independent of the FRK promoter methylation density." (PMID 28077797, 2017). "FRK was found to be expressed predominantly in mammary epithelial cells; however, its correlation to breast cancer cell subtype or stemness has not been reported." (PMID 29348886, 2017). "It is therefore likely that DAC could have induced the expression of FRK without demethylating any of the CpG sites in the promoter region as was noted when the hypomethylated BT20 breast cancer cells were treated." (PMID 28077797, 2017). "Fyn-Related Kinase (FRK) is a non-receptor tyrosine kinase coded by FRK located on chromosome 6q21–23, a region that displays loss of heterozygosity (LOH) in nearly 30% of breast cancers." (PMID 28077797, 2017).
glioma (8 papers, 2015 to 2024). A benign or malignant brain and spinal cord tumor that arises from glial cells (astrocytes, oligodendrocytes, ependymal cells). "FRK inhibits glioma cell migration and invasion by interacting with the N-cadherin/β-catenin and with the JNK/c-Jun signalling pathways." (PMID 35715818, 2022). "For instance, FRK inhibits cell proliferation, migration and invasion in glioma cells by promoting N-cadherin/β-catenin complex formation, inhibiting cyclin D1 nuclear accumulation and regulating JNK/c-Jun signaling." (PMID 29348886, 2017). "FRK controls the migration and invasion of human glioma cells by regulating JNK/c-Jun signaling." (PMID 39257581, 2024). "The oncosuppressor role of FRK has been reported in adult gliomas." (PMID 35715818, 2022). "We also observed a reduction in pAkt levels (PI3K/Akt signaling) and decrease in the levels of pMEK 1/2, p-p38 (MAPK signaling) and pJNK pathways were also inhibited in the presence of FRK In glioma cells, FRK was reported to reduce cell migration and invasion via inhibiting JNK activation." (PMID 29348886, 2017). "Also, FRK was shown to suppress glioma cell migration and invasion by regulating JNK/c-Jun signaling and promoting N-cadherin/β-catenin complex formation." (PMID 29348886, 2017). "FRK have been shown to suppress EMT markers in glioma cells." (PMID 29348886, 2017).
lung carcinoma (5 papers, 2018 to 2024). "(2020) evaluated the possible effect of the genetic depletion of Fyn-related kinase (FRK) by CRISPR/Cas9 in lung carcinoma H1299 cells to elucidate its role in NSCLC pathogenesis." (PMID 35508982, 2022). "In a further trial, researchers investigated the role of the FRK oncogene in the H1299 lung cancer cell line, demonstrating that knockout of FRK suppressed epithelial to mesenchymal transition cell colony formation and proliferation of cancer cells." (PMID 32796761, 2020). "Overexpression and hyperphosphorylation of FRK is reported in many cancer types, including lung cancer." (PMID 29556515, 2018). "On top of that, by a reverse genetics approach, it has been shown that the EMT inducer Fyn-related kinase (FRK) promotes glucose uptake and glycolytic metabolism in lung cancer models." (PMID 32932943, 2020).
pancreatic cancer (5 papers, 2017 to 2022). "FRK is overrepresented in our recent kinomic investigation of pancreatic cancer, providing additional evidence for FRK as an oncogene in malignancies of pancreatic origin." (PMID 33233470, 2020). "In pancreatic cancer, lung cancer, and liver cancer, FRK demonstrates oncogenic functionality." (PMID 33233470, 2020).
breast tumor (3 papers, 2010 to 2017). "However, several putative SRC substrates, including HIPK3, STAT5A, p120, FRK and Hrs, were frequently phosphorylated in multiple breast tumors." (PMID 21049007, 2010). "Analysis of the overlap between substrates phosphorylated in our study and in human tumors defined a group of proteins that may be most relevant to Src activity in human cancers: HIPK3, STAT5A, p120, Hrs and FRK in human breast tumors, and p130Cas, p120, FRK, Hrs and KIAA0323 in human lung tumors." (PMID 21049007, 2010). "We, however, did not see an inverse correlation between FRK and Fibronectin/Vimentin in the breast tumor samples." (PMID 29348886, 2017).
hepatocellular carcinoma (3 papers, 2020 to 2024). A malignant tumor that arises from hepatocytes. "FRK acts as an oncogene in hepatocellular carcinoma, contributing to enhanced proliferation and anchorage-dependent growth in liver cancer cells." (PMID 32082487, 2020).
liver cancer (3 papers, 2017 to 2021). An epithelial or non-epithelial malignant neoplasm that arises from the liver. "Although, FRK-VK and VF mutants were shown to increase STAT3 phosphorylation in liver cancer." (PMID 29348886, 2017).
diabetes (2 papers, 2021 to 2024). "β-cell-specific overexpression of FRK renders mice more susceptible to diabetes induction after treatment with streptozotocin (STZ), a glucose homologue that is taken up by the GLUT2 transporter on β-cells and leads to DNA alkylation and apoptosis induction." (PMID 38346191, 2024). "The phenotype of β-cell-specific C3 knockout mice when exposed to the STZ model of diabetes induction was consistent with this hypothesis and in line with demonstrated phenotypes of FRK and PTEN deletion." (PMID 38346191, 2024). "The activation of FRK induces cytotoxic signals to the beta pancreatic cells in response to several cytokines or beta cell toxins (like streptozotocin), thus promoting the induction of diabetes." (PMID 33922358, 2021).
brain cancer (1 paper, 2017). A primary or metastatic malignant neoplasm affecting the brain. "Knocking down FRK in the immortalized non-tumorigenic mammary epithelial cell line, MCF10A, induced transformation; while, exogenous expression of FRK in breast and brain cancer cells inhibited cell proliferation, migration and invasiveness." (PMID 28077797, 2017).
E. coli infection (1 paper, 2024). "Protein network analysis indicated that genes such as FOS, CTLA4, APOA1, CEL, FRK, and AGTR1 had the strongest association with other genes, highlighting their crucial roles in E. coli infection." (PMID 39707535, 2024).
gastric cancer (1 paper, 2020). A primary or metastatic malignant neoplasm involving the stomach. "In order to assess the relevance of these five kinases in gastric cancer tumors, we analysed the mRNA and protein levels in 200 biopsies from gastric cancer patients, revealing that transcript and protein levels of FRK, DDR1, SRC were elevated in metastatic tissues regardless of tumor stage." (PMID 32082487, 2020).
glioblastoma (1 paper, 2024). The most malignant astrocytic tumor (WHO grade IV). "In contrast, the nonreceptor tyrosine kinase Fyn-related kinase (FRK) phosphorylates yes-associated protein (YAP) and induces its ubiquitin−mediated proteolysis, contributing to the inhibition of glioblastoma progression." (PMID 39679197, 2024).
head and neck squamous cell carcinoma (1 paper, 2022). A squamous cell carcinoma that arises from any of the following anatomic sites: lip and oral cavity, nasal cavity, paranasal sinuses, pharynx, larynx, and salivary glands. "Little is known about FRK in head and neck squamous cell carcinomas." (PMID 36362284, 2022).
Hyperglycemia (1 paper, 2025). An increased concentration of glucose in the blood. "While systemic CFB and CFD protect against hyperglycemia by generating C3a, an insulin secretagogue, intracellularly C3 in β cells protects against IL-1β–induced islet destruction via proapoptotic Fyn-related kinase (FRK) signaling independent of exogenous C3a." (PMID 40519170, 2025).
iron deficiency (1 paper, 2015). "Mice deficient in the FRK had decreased the circulating levels of thyroid hormone T3 associated with iron deficiency." (PMID 26295473, 2015).
renal cell carcinoma (1 paper, 2025). "TRIM44, a known tumor-suppressing gene, downregulates Fyn-related kinase (FRK) and promotes cancer progression in renal cell carcinoma." (PMID 40723250, 2025).
cancer (20 papers, 2010 to 2025). A tumor composed of atypical neoplastic, often pleomorphic cells that invade other tissues. "This suggests that loss of FRK expression may promote cancer growth or development in a particular cellular context." (PMID 28077797, 2017). "FRK has been shown to act as a growth inhibitor in several cancer cell lines, in part by inhibiting signalling pathways such as JAK/STAT, MAPK, Akt and the EGFR pathway." (PMID 39009935, 2025). "Fyn-related kinase (FRK) has been known to be repressed in cancer cells due to its promoter CpG methylation." (PMID 36969235, 2023). "FRK inhibition attenuates aerobic glycolysis in some cancer cell models, while studies performed in other cancer cell models suggest FRK inhibition increases proliferation by downregulating the FRK-PTEN axis." (PMID 33233470, 2020). "The gene encoding FRK maps to the chromosomal locus 6q22-q23.2, a region frequently deleted owing to loss of heterozygosity (LOH) in nearly 48% of cancers." (PMID 29348886, 2017). "Fyn-related kinase (FRK) is a member of the Src kinase family that is involved in cancer." (PMID 35054987, 2022). "Overall, the functionality of FRK in cancer remains controversial." (PMID 33233470, 2020). "This suggests that expression, regardless of subsequent kinase activity, may be integral to the role of FRK in cancer." (PMID 33233470, 2020). "This indicated that FRK protein expression was low/moderate in both normal and cancer tissues." (PMID 29348886, 2017). "There are suggestions that FRK may be oncogenic in some cancers." (PMID 28077797, 2017). "For example, EAS-specific unambiguous probes (n = 484) from the HM450K array were overlapped with promoters and gene bodies of 140 cancer driver genes, such as CTNNB1, DSP, FRK, HLA-A, NOX4, and TRIO." (PMID 40445831, 2025). "While the majority of SRC-related kinases have a positive role on cell proliferation and survival, the RAK/FRK (FYN-related kinase) inhibits growth when expressed in a number of cancer cell types." (PMID 25594057, 2014). "Fyn related Src family tyrosine kinase (FRK) is a non-receptor tyrosine-protein kinase whose role in cancer remains controversial." (PMID 36362284, 2022).
tumor (19 papers, 2010 to 2026). "Many tumor cells for which FRK acts as a tumor suppressor are deficient in PTEN, so this relationship provides only partial explanation." (PMID 33233470, 2020). "Among the tyrosine kinases, the SRC family kinases BLK and LCK as well as the SRC family-related kinase FRK were significantly downregulated in the pAKT-positive T3 xenograft tumor." (PMID 35454789, 2022). "Previous studies have shown the tumor suppressive role of FRK (Fyn-related kinase) by inhibiting cell proliferation, PTEN (Phosphatase and tensin homolog) degradation, and EGF receptor signaling in BC." (PMID 34685653, 2021). "Fyn-related kinase (FRK) is a member of the Src kinase family and plays a role in promoting or inhibiting tumor growth in different types of tumors." (PMID 33435956, 2021). "Initially pursued as a potential tumor suppressor, more recent experimental results support the characterization of Fyn-related kinase (FRK) as an oncogene." (PMID 33233470, 2020). "Early evidence suggests the tumor suppressor activity of FRK involves direct binding to retinoblastoma (Rb) proteins inside cellular nuclei." (PMID 33233470, 2020). "Evidence supports an alternative mechanism of FRK-mediated tumor suppression in which FRK downregulates epidermal growth factor receptor (EGFR) kinase." (PMID 33233470, 2020). "The SRC-related tyrosine kinase, FRK, was recently demonstrated to act as tumor suppressor by attenuating AKT/PI3Kinase signaling through its action on the phosphatidylinositol-3,4,5-trisphosphate 3-phosphatase, PTEN." (PMID 21049007, 2010). "Surprisingly, we found a downregulation rather than an upregulation of several Src kinase and Src kinase-related family members—i.e., B-lymphoid tyrosine kinase (BLK), lymphocyte-specific protein tyrosine kinase (LCK) and Fyn-related kinase (FRK)—in the AKT/mTOR-inhibitor-resistant tumor cells." (PMID 35454789, 2022). "While originally attributed a potential tumor-suppressive function, in recent years, further functional characterization revealed that FRK might potentially play an oncogenic role." (PMID 36362284, 2022). "BD treatment may induce ANXA2, TGFI, FN1, HSP90B1 down-regulation, and FRK up-regulation to inhibit tumor metastasis by regulating autophagy, hypoxia, β-catenin, and STAT3 signaling pathways." (PMID 34685653, 2021). "In breast and brain cancer, FRK demonstrates tumor suppressive functionality." (PMID 33233470, 2020). "Our data suggest that FRK could promote the inhibition of cell growth and migration by suppressing the activation of various signaling pathways, and more significantly the STAT3 signaling pathway and the tumor suppressor role of FRK could be tissue dependent." (PMID 29348886, 2017). "Other 6q15 genes with potential tumor suppressive functions for example include EEF1A1, ZNF292, SNORD50A, PRDM1, CCNC, FOXO3, WISP3, and FRK." (PMID 34625909, 2022). "In order to assess if the identified kinases in the invasion assay correlate with expression levels in tumors from GC patients, mRNA and protein expression levels for FRK, DDR1, SIK2 and SRC were assessed in tumor samples from GC patients." (PMID 32082487, 2020). "FRK (related to Src family of kinases) is known to be aberrantly phosphorylated in NSCLC and there are reports which indicate its dual role as tumor suppressor or promoter depending on cell type." (PMID 29556515, 2018). "For example, Src family kinases HCK, FRK and LYN are onco-homologs of PDGFRA/KIT, which interact with both PDGFRA and KIT as downstream effectors and play critical roles in tumor cell proliferation and survival." (PMID 29844492, 2018). "Based on this rationale, four potential genes (JARID2, FRK, DR5 and TGFBR3) were selected from the databases of miRwalk, miRanda and TargetScan according to their potential functions in tumor suppressive processes." (PMID 27129166, 2016). "Meanwhile, a previous study found that overexpression of FRK promoted tumor cell proliferation, invasion, and non-adherent cell growth." (PMID 37745847, 2023).
tumor (continued). "Levels of FRK, DDR1 and SRC expression on both mRNA and protein level were significantly higher in metastatic patient samples regardless of the tumor stage, while expression levels of SIK2 correlated with tumor size." (PMID 32082487, 2020). "More recent evidence indicates FRK directly binds and phosphorylates the phosphatase and tensin homolog (PTEN) tumor suppressor protein, protecting PTEN from degradation and maintaining its tumor suppressive effects." (PMID 33233470, 2020). "No obvious correlation was observed between FRK expression and the clinicopathological characteristics such as tumor grade and TNM in the small sample size used in this study." (PMID 29348886, 2017). "Overall, our data implied that activation of FRK was important but not essential for the tumor suppressor activity of the kinase." (PMID 29348886, 2017). "Substrates such as p120, Hrs, Ack, p130Cas and FRK may be key mediators of SRC signaling in human tumors and contribute directly to SRC-mediated events during tumor progression." (PMID 21049007, 2010). "FRK is a non-receptor tyrosine kinase with unpredicted tumor suppressor activity." (PMID 29348886, 2017). "No previous studies have examined the effect of FRK activation on its tumor suppressor function." (PMID 29348886, 2017). "In line with our findings in the metastatic cell line AGP-01, the median expression levels of both mRNA (measured by qPCR) and protein (assessed by Western blot) of FRK and DDR1 were higher in metastatic patient samples regardless of the tumor stage (P < 0.0001 Mann-Whitney U test)." (PMID 32082487, 2020). "Nonetheless, since stellate/FRK-negative MDA-MB-231 cell line is characterized as highly invasive and we observed that overexpression of FRK alters the morphology to rounded, we hypothesized that the tumor suppressor activity of FRK might play a significant role in the inhibition of cell invasion." (PMID 29348886, 2017).
infection (1 paper, 2023). The state of being infected such as from the introduction of a foreign agent such as serum, vaccine, antigenic substance or organism. "In addition, defense-related genes, including PR and FRK, exhibited significant up-regulated expression during the infection by MR-9." (PMID 37628875, 2023).
FRK also shares sentences with these, for which no sentence is quoted: hepatocellular adenoma (2 papers); Alzheimer disease (1); benign neoplasm (1); cervical cancer (1); congenital heart defects (1); fibrous dysplasia (1); leukemia (1); melanoma (1); metastatic tumors (1); oral squamous cell carcinoma (1); osteoarthritis (1); retinoblastoma (1).